GZMB (granzyme B)
Diseases named in the same sentence as GZMB in open-access papers (continued):
Sharing a sentence is not in itself a finding about the gene and the disease.
influenza (continued). "This is the first study to investigate the correlation between IFN-γ and granzyme B levels following influenza vaccination." (PMID 34199161, 2021). "Our previous work suggests that granzyme B (GrB) activity predicts protection against laboratory-confirmed influenza infection (LCII) in older adults." (PMID 35441156, 2021). "We have shown that granzyme B (GrB) activity in influenza A/H3N2 challenged peripheral blood mononuclear cells (PBMC) correlates with protection against influenza following standard dose vaccination (SD-SVV) in older adults." (PMID 35128529, 2021). "First, since none of the subjects were exposed to influenza virus, we were unable to examine the level of granzyme B in response to influenza infection." (PMID 34199161, 2021). "Total CD4 T cell reactivity at any time point was defined as the total number of cells that produce any of the 4 effector responses (IFNγ, Granzyme B, IL-4 and IL-10) to the different MPs from all 4 influenza strains." (PMID 33922875, 2021). "In the present study, we used our method to quantify IFN-γ and granzyme B production in whole blood from influenza-vaccinated individuals in response to influenza antigens." (PMID 34199161, 2021). "Granzyme B is an important effector in CTL-mediated immune responses, particularly in diminishing influenza-associated complications in the elderly." (PMID 32788837, 2020). "Geometric mean granzyme B levels to all influenza strains were present prior to vaccine receipt in all study groups and were sustained throughout the observation period." (PMID 32698532, 2020). "When using functional assays of CD8+ T cell cytolytic activity upon ex vivo influenza challenge, CMV-seropositivity was associated with impaired cytolitic responses to influenza, measured by granzyme B levels in virus-challenged T cells." (PMID 33178213, 2020). "Hemagglutination-inhibition assays, antibody to Influenza A virus nucleoprotein and peripheral blood mononuclear cells for measurement of interferon-gamma ELISPOT response to influenza antigens, Granzyme B and IFNγ:IL-10 ratio were measured." (PMID 32698532, 2020). "NK cells activation contributes to destruction of influenza-infected cells via secretion of perforins, granzyme B, and IFN-γ." (PMID 33183352, 2020). "The production of granzyme B from influenza virus‐stimulated PBMCs predicted protection from influenza vaccination." (PMID 31044512, 2019). "Natural killer cell effector molecules IFN-γ and GzmB were produced by influenza-infected explants 24 hpi." (PMID 30079068, 2018). "Compared to vaccination with inactivated influenza alone, the addition of CpG induced significantly higher GzmB expression in lung CD4 T cells, which persisted after challenge with lethal PR8 infection." (PMID 28167943, 2017). "Aside from the primary CMI assays, additional T cell based assays such as dual ELISpot (IFN-γ and granzyme B) will be performed as an exploratory endpoint since ELISpot has shown to be a sensitive assay to measure influenza-specific CMI." (PMID 28376743, 2017). "Lower IFNγ:IL-10 ratios and levels of the cytolytic mediator, granzyme B, in influenza-challenged peripheral blood mononuclear cells (PBMC) correlate with increased risk of influenza in vaccinated older adults." (PMID 26941738, 2016). "We have shown that older people who develop influenza illness have low levels of the cytolytic mediator, granzyme B (GrB), and a lower ratio of IFNγ:IL-10 released from peripheral blood mononuclear cells (PBMC) following challenge with live influenza virus." (PMID 27322555, 2016). "Granzyme B (Grz B) is a key component of perforin-mediated killing by CTL, and low levels of GrzB activity generated in response to influenza challenge following vaccination predict increased risk and severity of influenza illness in older adults." (PMID 26941738, 2016).
influenza (continued). "Classically, NK cell effector functions include release of IFNγ and direct cytotoxicity to influenza-infected cells by granule exocytosis (e.g., granzyme B and perforin)." (PMID 23441208, 2013). "An increase in granzyme B expression in influenza-specific T cells in response to influenza challenge in older individuals has been correlated with improved immunity to influenza." (PMID 23474627, 2013). "Next, we investigated the roles of cytokines for IFN-γ production and granzyme B induction by NK cells to influenza infection in vivo." (PMID 23300570, 2012). "The influenza-specific cell-mediated immunity, and particularly granzyme B-producing cytotoxic T-lymphocytes, appear to be critical for protection against disease." (PMID 22457731, 2012). "In contrast to STAT1−/− NK cells, STAT4−/− NK cells were defective for IFN-γ production, but displayed WT levels of granzyme B induction following influenza infection." (PMID 23300570, 2012). "In both PR8 and A/California stimulations, about 1/3 of the influenza responsive CD8 T cells were also granzyme B+." (PMID 21887299, 2011). "Increased levels of IFN-γ following influenza vaccination are positively correlated with the levels of granzyme B, which could implicate either NK or T cells." (PMID 40881708, 2025). "It has also been found that NK cells in mice vaccinated with a multivalent influenza vaccine had greater expression of granzyme B and perforin and took on a more mature phenotype after being challenged by heterosubtypic influenza strains compared to unvaccinated mice." (PMID 37928543, 2023). "Vaccine-specific CD8 T cells produced predominantly IFNγ cytokines and displayed high Granzyme B activity, a phenotypic profile that was reported to be protective from not only symptomatic influenza infection, but also from severe complications in the 2009 H1N1 pandemic." (PMID 33922875, 2021). "The granzyme B assays demonstrate dose-dependent CHM1319/HLA-A*02:01-specific T cell-mediated killing of T2 cells loaded with CHM1319 compared to T2 cells loaded with influenza-derived control peptide." (PMID 34831294, 2021). "An addition, SFN-rich broccoli homogenate attenuated granzyme B production in NK cells that was induced by influenza virus and granzyme B production in NK cells, and granzyme B levels appeared to have negatively interacted with influenza RNA levels in nasal lavage fluid cells." (PMID 34202844, 2021). "This suggests that the IFN-γ and granzyme B responses to influenza vaccines are similar." (PMID 34199161, 2021). "Similar and upregulation of granzyme B were observed in influenza both in vivo and in vitro." (PMID 35381137, 2021). "Moreover, our study suggests that both IFN-γ and granzyme B can be examined to evaluate the efficacy of influenza vaccines in eliciting cell-mediated immunity." (PMID 34199161, 2021). "Hence, influenza vaccine, such as FP-01.1, which can stimulate granzyme B activity in influenza vaccination programme must be included." (PMID 32788837, 2020). "Natural killer (NK) cells have also been shown in mouse models to contribute to the control of influenza during the early stage of infection through granule-mediated (granzyme B and perforin) killing of virus-infected cells, but can also be killed themselves by the influenza virus." (PMID 32399058, 2020). "On the other hand, other studies have demonstrated that ex vivo T cell parameters (e.g., interferon (IFN)-gamma and IL-10 ratio, granzyme B levels) measuring cellular immune responses to influenza challenge performed better than antibody titers as correlates of vaccine efficacy in older adults." (PMID 33178213, 2020). "Furthermore, it was reported that immunosenescent cells produce less granzyme B in response to influenza vaccination." (PMID 30544783, 2018).
influenza (continued). "However, little is known about the relationship between IFN-γ and granzyme B. In the present study, we evaluate the effect of the inactivated influenza vaccine on cell-mediated immunity by quantifying the IFN-γ and granzyme B levels before and after vaccination." (PMID 34199161, 2021). "In the present study in both HMPV and influenza infection, aged Pdcd1−/− CD8+ T cells exhibited increased granzyme B production, which was recapitulated in the transplant experiments." (PMID 38015461, 2023). "The correlation observed between number of cells secreting IFN-γ or granzyme B in response to FLU-v and to the influenza strains supported vaccine-induced cross-reactivity." (PMID 36146606, 2022). "We noted increased expression of genes related to cytotoxicity, activation and inflammation—such as GZMB, GNLY, TYROBP, HOPX, and CCL5—in the CD8 EMRA-like two cluster that was expanded in CAP-flu." (PMID 34424199, 2021). "In the case of influenza reactive CD8 T cells, both Granzyme B (p = 0.0002) and IFNγ (p = 0.0059) producing CD8 T cells dominated the pre-existing CD8 T cell responses at baseline." (PMID 33922875, 2021). "Compared with healthy weight individuals, participants with obesity show a greater decline in influenza antibody titers, CD8+ T cell activation, and expression of functional proteins (IFN-γ and granzyme B) 12 months after influenza vaccination." (PMID 34373739, 2021). "Then, we examined the correlation between the IFN-γ and granzyme B levels and found a significant correlation between the two, revealing that IFN-γ and granzyme B responses to the influenza vaccine occur in a similar manner." (PMID 34199161, 2021). "It is known from influenza vaccine research that granzyme B correlates with protection and enhanced CTL response to influenza vaccination in older adults." (PMID 34394127, 2021). "Even though most pathways were activated in most treatments, “Granzyme B Signaling” in the first age transition, and “Role of Wnt/GSK-3β Signaling in the Pathogenesis of Influenza” in the second transition, were both suppressed under all exposure scenarios." (PMID 32015368, 2020). "This universal influenza vaccine candidate is especially effective in the elderly population; it significantly induces the production of IFN-γ, IL-2 and granzyme B in vaccinated persons." (PMID 32788837, 2020). "Importantly, NK cells from DPI 2 that express the IL-27R (Wsx-1) are the ones that also produced IFN-γ and granzyme B demonstrating a causal relationship between the expression of IL-27R and NK cell effector functions during influenza infection (data not shown)." (PMID 30899058, 2019). "We identified early activation of NK cells in response to influenza-infected cells, including IFN-γ and GzmB production, degranulation, and cytotoxicity." (PMID 30079068, 2018). "High baseline levels of granzyme B in CMV-positive individuals are associated with a poor granzyme B response to influenza challenge, and may negatively impact on protection against serious influenza illness and the response to influenza vaccination when compared to CMV-negative elderly." (PMID 23474627, 2013). "We found that granzyme B was expressed in a greater proportion of the influenza reactive IFNγ positive CD8 T cells from older donors, however, as has been shown by others, granzyme B is also overexpressed in the total CD8 T cell population of 65+ donors." (PMID 21887299, 2011). "Almost half of influenza-specific CD8 T cells produced only IFNγ However, a significant proportion of the T cells also made granzyme B and there were also small but detectable populations of T cells that produced other combinations of effector molecules." (PMID 22132212, 2011). "Similarly, influenza-infected aged mice lost more weight, produced fewer tetramer+ CD8+ T cells, had impaired granzyme B production, and accumulated more TCF1/7− TOX+ EOMES+ CD8+ T cells." (PMID 37528458, 2023).
influenza (continued). "Aged influenza-infected mice failed to produce granzyme B or have any granzyme B functional tet+ CD8+ T cells." (PMID 37528458, 2023). "PBMC sampled pre- (day 0) and post-vaccination (days 42 and 180) from vaccine (n = 58) and placebo (n = 27) recipients were tested in vitro for responses to FLU-v and inactivated influenza strains (A/H3N2, A/H1N1, A/H5N1, A/H7N9, B/Yamagata) using IFN-γ and granzyme B ELISpot." (PMID 36146606, 2022). "If the immune response to influenza infection is similar to the immune response to the vaccine, IFN-γ and granzyme B could serve as important additional indicators for evaluating the effectiveness of the vaccine." (PMID 34199161, 2021). "In summary influenza infection is capable of inducing MAIT cells to upregulate antiviral IFN-γ, and cytolytic granzyme B in a TCR-independent manner, requiring production of IL-18 and potentially other mediators from accessory cells including monocytes and macrophages." (PMID 35381137, 2021). "Third, the underlying mechanisms of MCEMP1 and SPARC genes contributing to the development of protective immunity after influenza vaccination should have been rigorously verified in multidimensions, especially the regulation of effector cytokines (CXCL 8/IL-8, Granzyme-B)." (PMID 33343577, 2020). "In contrast, no Perf/GzmB+ events were detected among a coexisting influenza M143–59–specific CD4+ T cells in this donor, or any other patients with IM (n = 5), excluding the possibility of bystander CD4+ T cell activation." (PMID 31308093, 2019). "Furthermore, NK cells provided significant antiviral, cytotoxic activity following contact with influenza-infected cells, including the production and release of IFN-γ and granzyme-B resulting in macrophage cell death." (PMID 30079068, 2018). "Additionally, Vγ9Vδ2 T cells have the ability to lyse influenza infected cells using a mechanism that depends greatly on NKG2D and granzyme B." (PMID 25785862, 2015). "Vaccination also did not appear to affect the frequency of influenza-specific CD4+ or CD8+ T cells expressing Granzyme B and at least IFN-γ, and/or IL-2." (PMID 25078387, 2014). "Influenza vaccinated HCMV seropositive individuals >65 years of age had impaired in vitro inducible granzyme B release to influenza virus, but there was no apparent effect on antibody responses to standard titer or high titer influenza vaccination according to HCMV status." (PMID 32582177, 2020). "Although granzyme B and IFN-γ are induced in lung explants after influenza infection, and enhanced IFN-γ responses are detected in peripheral blood NK cells following influenza vaccination, there is no direct evidence that granzyme B and IFN-γ are released by lung NK cells." (PMID 31293580, 2019). "As such, the fact that we could not observe an induction of Lag-3, Tim-3, or Granzyme B following influenza vaccination in human Treg cells might be a consequence of the narrow window of analysis." (PMID 29951069, 2018). "The granzyme B levels in peripheral NK cells In the BSH, but not the ASH group, appeared to be negatively associated with Influenza RNA levels in nasal lavage fluid cells, which may have played a role in reducing replication of LAIV in the nasal cavity." (PMID 26820305, 2016).
colorectal cancer (59 papers, 2010 to 2026). A primary or metastatic malignant neoplasm that affects the colon or rectum. "Studies have confirmed that CD8+ T cell infiltration is associated with a good prognosis in triple-negative breast cancer, and high mRNA expression of GNLY and GZMB in tumors is associated with a good prognosis in colorectal cancer." (PMID 40860340, 2025). "One study showed that upregulated mRNA expression of intratumoral GNLY and GZMB was associated with a favorable outcome in patients with colorectal cancer." (PMID 39643914, 2024). "For instance, patients with colorectal cancer more commonly had high expression of GZMB and ICOSLG (Relative risk [RR]: 1.87 and 1.46, respectively)." (PMID 37553332, 2023). "GZMB expression was associated with worse clinical outcomes in non-small-cell lung cancer and with early signs of metastasis in colorectal cancer." (PMID 36601599, 2022). "However, co-culturing CD8+ T cells with Psat1- or Shmt2-deficient colorectal cancer cells showed enhanced cytotoxic activity, as indicated by increased Granzyme B levels detected via flow cytometry." (PMID 40475762, 2025). "In addition, GZMB expression in colorectal cancer was associated with pathological tumor spreading and EMT." (PMID 32764784, 2020). "CKT manufactured TCR-T cells demonstrated higher 4-1BB upregulation, IFN-γ, TNF, and granzyme B (GZMB) production, and enhanced killing of pancreatic and colorectal cancer cell lines in 2D and 3D tumor spheroid co-culture." (PMID 42220480, 2026). "D’Eliseo D confirmed this influence in colorectal cancer cells, showing that GZMB plays a role in TGF-β1-induced EMT." (PMID 41567188, 2025). "Compared to traditional CAR-NK cells, the GPR132-downregulated CAR-NK cells displayed enhanced cytotoxicity against colorectal cancer cells and increased the expression of GzmB and IFN-γ." (PMID 40043109, 2025). "The deficiency of GPR132 can attenuate the inhibition of NK cells by lactate, consequently increasing the expression of INF-γ and GzmB and effectively boosting the anti-colorectal cancer effect of CAR-NK92 cells." (PMID 40043109, 2025). "Granzyme B has been reported to be an up-modulator of EMT and invasion in colorectal cancer cells, and DHA inhibits urothelial, pancreatic, and colorectal carcinoma cell invasion and their granzyme B expression." (PMID 39684816, 2024). "Adoptive transfer of activated B cells into a model of colorectal cancer can reduce liver metastasis and increase liver infiltration of cytotoxic granzyme B (GzmB) + T cells." (PMID 37215990, 2023). "Strikingly, we found that IT delivery of low doses of MMR correlates with tumor control and improved survival in murine hepatocellular cancer and colorectal cancer models via increased tumor infiltration of CD8+ granzyme B+ T-cells and decreased macrophages." (PMID 36457491, 2022). "Regarded as an endogenous inhibitor of Granzyme B, higher expression of SERPINB9 in patients with colorectal cancer was associated with superior OS." (PMID 36249755, 2022). "Intensive studies have been conducted and found that LINC02474 restrained GZMB expression to suppress the proliferation and metastasis of colorectal cancer cells." (PMID 35464869, 2022). "The low expression of GZMB is related to early metastasis in colorectal cancer, suggesting the infiltration of blood vessels and nerves." (PMID 34906145, 2021). "Previous studies have confirmed that CD4+ GzmB+ T cells were involved in the antitumor immune response of bladder cancer, non-small cell lung cancer, and colorectal cancer." (PMID 34631551, 2021). "It has been reported that the number of granzyme B-expressing cells present in colorectal cancer tissue correlates with the prolonged survival of patients." (PMID 34944392, 2021). "The increased level of granzyme-B in serum or tumor was correlated with favorable outcomes in patients with colorectal cancer or NSCLC." (PMID 33918641, 2021).